HIF1A (hypoxia inducible factor 1 subunit alpha)
Diseases named in the same sentence as HIF1A in open-access papers (continued):
Sharing a sentence is not in itself a finding about the gene and the disease.
lung carcinoma (continued). "In yet another study, both mRNA and protein levels of HIF-1α were shown to be reduced after miR-200c transfection in hypoxic lung cancer." (PMID 33673143, 2021). "To further confirm the correlation between IL1A, IL6, and HIF1α, we analyzed the expression of these two genes in 16 patients with lung cancer." (PMID 34362882, 2021). "The involvement of Akt activation and HIF-1α is a crucial element in lung cancer metabolic dysregulation given that Akt is upstream to many metabolism-regulating pathways and HIF-1α drives the Warburg effect forward." (PMID 33916349, 2021). "HIF-1α, generally highly expressed in lung cancer cells, is considered as the main mediator of lung cancer cells under hypoxia." (PMID 34044859, 2021). "Since HIF-1α plays an important role in the progression of lung cancer, the effect of HIF-1α inhibitors on lung cancer was studied." (PMID 34829545, 2021). "Despite this, within pulmonology, to date, variations within the HIF1A gene have only been associated with COPD and lung cancer." (PMID 34621299, 2021). "STAT3 is downregulated by resveratrol administration concomitantly with an attenuation of HIF-1α as well as VEGF levels in xenograft models of lung cancer, indicating the inhibitory function of resveratrol in hypoxia-mediated angiogenesis." (PMID 34575983, 2021). "Hypoxia was further characterized in different preclinical models of BM from lung cancers (H2030-Br3M, H1915; via intracerebral and intracardiac injections) using immunohistological staining (pimonidazole, HIF-1α) as well as imaging approaches." (PMID 34045576, 2021). "Results from recent studies have shown that high expressions of AK4 promote lung cancer metastasis by enhancing HIF-1α stability and EMT under conditions of hypoxia." (PMID 34217310, 2021). "HIF-1α plays an important role in the development of VM in lung cancer by upregulating NRP1, indicating the potential therapeutic value of targeting NRP1 for the suppression of NSCLC metastasis and progression." (PMID 33850110, 2021). "A previous study found that HIF-1α expression affected tumor proliferation and apoptosis in surgically resected lung cancer." (PMID 35280249, 2021). "Up-regulating miR-449a hindered while suppressing miR-449a induced lung cancer development via mediating HIF-1α." (PMID 34044859, 2021). "For Warburg effect, previously study also found that IDH2 promoted the Warburg effect and lung cancer cell growth, which is mediated through HIF1α activation followed by decreased α-KG." (PMID 34513821, 2021). "To study the effects of hypoxia on lung cancer development, we analyzed HIF1α expression in the normal and tumor tissues using the TCGA database." (PMID 34362882, 2021). "We next assessed PRAK and HIF-1α protein expression using immunohistochemistry in a human tissue array containing 40 lung carcinoma samples with paired lymphatic metastases." (PMID 33741957, 2021). "In lung cancer, it was demonstrated that HIF-1α binds to the hypoxia-element in the FOXC1 promoter and drives FOXC1 transcription, resulted in enhanced tumor progression." (PMID 33854062, 2021). "It was found that DPT significantly inhibited HIF-1α signaling in both lung cancer cell lines, indicating impairment ofHIF-1α-dependent signaling." (PMID 33732648, 2021). "Induction of Sema4D by hypoxia through a HIF-1α-dependent mechanism has been also evidenced in lung cancer, and up-regulation of a disintegrin and ADAM17 expressions by hypoxia has been identified as the cause of Sema4D induction." (PMID 33858502, 2021). "In conclusion, our results suggest that HIF‐1α is essential for the activation and tumour‐promotion function of CAFs in lung cancer (LC)." (PMID 33943003, 2021).
lung carcinoma (continued). "It is eventually concluded that miR-449a delays lung cancer development through suppressing KDM3A/HIF-1α axis." (PMID 34044859, 2021). "The expression of CDK8 and SUB1 was also higher in lung cancer patients with high HIF1α expression, further suggesting the upregulation of CDK8 and SUB1 by hypoxic stress." (PMID 34362882, 2021). "Previous results in mouse mammary and 3LL lung carcinoma tumor models indicate that hypoxia-driven HIF-1α activation in MΦ advances their polarization towards the anti-inflammatory M2 phenotype." (PMID 34479492, 2021). "Inhibition of Hsp70 reverses the effect of thermal stimulation on lung cancer by reducing the SUMO modification of HIF-1α." (PMID 34868316, 2021). "On the whole, it is summarized that miR-449a interacts with KDM3A/HIF-1α axis, and performs anti-tumor effects on lung cancer." (PMID 34044859, 2021). "MiR-18-5p was reported to be a potential target for improving radiosensitivity in lung cancer by regulating the ataxia telangiectasia mutated (ATM) gene and hypoxia-inducible factor 1 alpha (HIF-1α) gene." (PMID 34572367, 2021). "LINC00301 can facilitate lung cancer progression and triggers an immune-suppressing microenvironment through regulating the HIF1α." (PMID 34355042, 2021). "So we co‐stained the HIF‐1α and α‐SMA in lung cancer tissues and normal lung tissues, our results demonstrated that HIF‐1α was highly expressed in CAFs of human LC tissues and mouse spontaneous LC tissues." (PMID 33943003, 2021). "The accumulated HIF-1α increases ROS levels and converts cellular metabolism into aerobic glycolysis under prolonged hypoxia, promoting metastasis of lung cancer cells." (PMID 34277453, 2021). "Another interesting link, although only described in lung cancer, is the positive feedback loop composed of miR-199a-5p/HIF1-α and STAT3." (PMID 35008579, 2021). "The Hsp70-specific inhibitor Apoptozole reverses the effect of thermal stimulation on lung cancer by reducing the SUMO modification of HIF-1α." (PMID 34868316, 2021). "In response to hypoxia, miR-200c negatively regulates hypoxia-induced cellular responses by downregulating HIF-1α, leading to a decreased mRNA level of HIF-1α downstream genes and an inhibited metastasis of lung carcinoma cells." (PMID 34277453, 2021). "In this study, we found that hypoxia‐inducible factor‐1α (HIF‐1α) was highly expressed in CAFs of human lung cancer tissues and mouse spontaneous lung tumour." (PMID 33943003, 2021). "Up-regulating KDM3A or HIF-1α negated up-regulated miR-449a-induced effects on cellular growth in lung cancer." (PMID 34044859, 2021). "The depletion of long non-coding RNA cancer susceptibility 9 suppressively modifies the proliferation, invasion and migration of lung cancer, which is connected with its positive feedback loop with HIF-1α." (PMID 34044859, 2021). "For example, MB mRNA expression correlated with HIF1α (r = 0.483) or VEGFa (r = 0.468) in lung cancer tissue samples." (PMID 33996536, 2021). "HPV16 E6 is also able to hinder the von Hippel-Lindau (VHL)/HIF1α interaction and thus to increase GLUT1 expression and the Warburg effect by activating HIF1α in lung cancer cells." (PMID 33807087, 2021). "First, functional studies show KLF5 co-immunoprecipitates with HIF-1α, which is consistent with previous studies in lung cancer cells." (PMID 33430300, 2021). "Thermal stimulation upregulated the expression of Hsp70 and promoted SUMO modification of HIF-1α, ultimately promoting the proliferation and metastasis of lung cancer." (PMID 34868316, 2021). "Accordingly, hypoxia significantly protected A549 and SPC-A1 lung cancer cells from cisplatin-induced cell death in a HIF-1α- and HIF-2α-dependent manner." (PMID 35127467, 2021). "Compared with NFs, the gene expressions of Hif1a were higher in CAFs of human lung cancer tissues and mouse lung cancer tissues." (PMID 33943003, 2021).
lung carcinoma (continued). "Recently, rearing of rats under 10% hypoxia for 14 days suppressed tumor progression in lung cancer via suppression of HIF-1α." (PMID 33918929, 2021). "To further investigate the antitumor effects of MYC and HIF1α inhibition in vivo, we first explored xenograft model using H1944 cells which were originally from a non–small cell lung cancer patient." (PMID 33572152, 2021). "It has been previously reported that the activation of ERK signaling is involved in triggering HIF-1α-induced EMT in lung cancer cells." (PMID 33374849, 2020). "The results showed that HIF-1α mRNA expression was positively correlated with ANGPT2 both at lung cancer cell lines (r=0.513, P=0.007) and lung cancer tissues (r=0.285, P<0.001)." (PMID 31892982, 2020). "Upstream PKA activators modulate HIF-1α transcriptional activation of target genes such as VEGF-A in lung cancer models." (PMID 32111982, 2020). "Baicalin can reduce lung cancer metastasis by reducing HIF-1α level and can reduce the expression levels of RAGE, IL-6, and TGF-β1 to improve pulmonary hypertension." (PMID 33149752, 2020). "NSCLC is often associated with a hypoxic environment leading to HIF-1α overexpression, and HIF-1α knockdown in the NCI-H157 lung carcinoma cell line has been shown to reduce VEGF-A expression and cell invasiveness." (PMID 32085654, 2020). "HIF1α plays a crucial regulatory effect on the occurrence and development of various categories of cancers including lung cancer." (PMID 32878637, 2020). "In previous studies, basal level of HIF-1α expression is high in lung cancer mouse model in normoxic condition even though the level of HIF-1α is increased in hypoxic conditions." (PMID 32024881, 2020). "They found that lung cancer cells, human patient tissues, and cells treated under hypoxia environment, both type cells presented increased expression of HIF1-α (hypoxia-inducible factor 1 alpha) protein that in turn increased the expression of miR-301b." (PMID 33273694, 2020). "We have previously shown that VDAC1-ΔC formation is mitochondrial and is dependent on nuclear HIF-1α in a lung cancer model." (PMID 32194829, 2020). "In various types of lung cancer, the HIF-1α/VEGF axis is activated in the hypoxic tumor microenvironment, which promotes angiogenesis and maintains cancer growth." (PMID 32112644, 2020). "Previous studies also displayed that HIF‐1A was involved in the proliferation and apoptosis process of non‐small cell lung cancers." (PMID 32061057, 2020). "In non–small cell lung cancer, the inhibition of HIF‐1α enhances the antitumor effect of radiation through the Notch pathway." (PMID 32436609, 2020). "Our result showed that PARP1 and HIF1A have 41 known lung cancer-specific (hypergeometric test p-value < 1.0E–20) and 30 clinically relevant (p-value = 0.04) synthetic lethal interactions between their OCRs." (PMID 31097707, 2019). "In this study, the effect of YC-1, a putative inhibitor of hypoxia-inducible factor-1α (HIF-1α), on hypoxia-induced TF expression was investigated in human lung cancer A549 cells." (PMID 30634531, 2019). "Hypoxia is able to directly drive angiogenesis in lung cancer by activating the HIF-1α/VEGF signaling pathway." (PMID 31817513, 2019). "HIF-1 is known to enhance the expression of many glycolytic enzymes, and miR-199a has been reported to inhibit lung cancer proliferation by suppressing HIF-1α and affecting the glycolytic pathway." (PMID 30935143, 2019). "ALDOA (aldolase, fructose-bisphosphate A), one of the NRF2-regulated genes identified in our ChIP-Seq results, promotes the metastasis of lung cancer by activating the HIF-1α/MMP9 axis." (PMID 31884422, 2019). "Overexpression of AK4 promotes lung cancer metastasis by enhancing HIF-1α stability and EMT under hypoxia." (PMID 30696468, 2019). "In an orthotopic xenograft model of lung cancer, the HIF-1α antagonist PX-478 effectively inhibits tumor progression." (PMID 30696468, 2019).
lung carcinoma (continued). "In lung cancer, both small cell and non–small cell lung cancers express high levels of HIF-1α, but its role as a prognostic factor remains controversial." (PMID 30696468, 2019). "In this study, we found that HIF-1α is downregulated by miR-18, −200c and − 549 at the mRNA and protein levels in lung carcinoma cells." (PMID 31061665, 2019). "In KRAS mutant lung cancer cells, it was discovered that Sirt3 was significantly up-regulated in honokiol-treated KRAS mutant lung cancer cells, leading to the destabilisation of its target gene Hif-1α and induction of G1 arrest and apoptosis." (PMID 31877856, 2019). "Our findings support HIF-1α as a potential biomarker of bone metastasis and an indicator of poor prognosis in lung cancer." (PMID 31903166, 2019). "Similar results were reported in A549 lung cancer cells, that HIF-1α protected A549 cells from drug-induced apoptosis." (PMID 31849679, 2019). "In this study, we show that HIF-1α, a key regulator of hypoxia signaling, is negatively regulated by miR-200c in lung carcinoma cells." (PMID 31061665, 2019). "ALDOA stabilizes the HIF1α protein and forms a positive feedback pathway to promote lung cancer metastasis." (PMID 31601833, 2019). "Akt1 phosphorylation was also increased in hypoxic A549 cells; HIF-2α expressing lung cancer cells had a higher phospho-Akt1 expression compared to control or HIF-1α expressing cells." (PMID 31817513, 2019). "Taken together, these results strongly suggest that PARP1 and HIF1A are effective combinatorial therapeutic targets for lung cancer." (PMID 31097707, 2019). "In our previous work, we found that the overexpression of HPV16 E6/E7 up-regulated the expression of HIF-1α which further up-regulated GLUT1 expression in lung cancer cells." (PMID 31839825, 2019). "The purpose of this investigation was to identify the acute redox changes in radiation-resistant lung cancer cells treated with a radiosensitizing HIF-1α inhibitor." (PMID 29891977, 2018). "A contribution of the HIF-1α/VEGF axis to cisplatin-induced antiangiogenesis was additionally reported for lung cancer cell lines containing exon 19 deletions in the epidermal growth factor receptor (EGFR)." (PMID 30344920, 2018). "CXCR4, CK7, CDH1, CTNNB1 and HIF1A showed significant upregulation in primary lung cancer as compared to liver metastasis." (PMID 30383826, 2018). "To further confirm the promoting role of HIF-1α in lung cancer, we have developed a mouse with overexpression of HIF-1α in the airway epithelium by crossing a CCSP-rtTA mouse to HIF-1α Tg mouse (CCSP-rtTA/HIF-1α Tg mouse)." (PMID 30250643, 2018). "In lung cancer, TRM cells had elevated expression of genes related to hypoxia, such as HIF1A (which encodes HIF-1α) and EPAS1 (which encodes HIF-2α)." (PMID 30180905, 2018). "When lung cancer cells proliferate, tumor volume and oxygen consumption increase significantly, the cancer cells become hypoxic and overexpress HIF-1α, which leads to the secretion of angiogenic factors (Ang-2, VEGF and so on) and induces angiogenesis." (PMID 29560103, 2018). "We recently showed that a radiation-resistant isogenic line of human A549 lung cancer cells had significantly elevated expression of hypoxia-inducible factor (HIF-1α), and increased glucose catabolism compared with the parental, radiation-sensitive cell line." (PMID 29891977, 2018). "For instance, the crosstalk between important transcription factors such as NRF2 and hypoxia-inducible factor (HIF)-1α is a very interesting example in lung cancer." (PMID 29050246, 2017). "Knockdown of HIF-1α can sensitize human colon cancer, neuroblastoma, uterine cervical cancer, lung cancer, and gastric cancer cells to TRAIL-mediated apoptosis." (PMID 28476028, 2017).
lung carcinoma (continued). "Cheng and coworkers showed in A549 lung cancer cells that miR-622 directly binds to the 3 ́-untranslated region of HIF-1α mRNA and decreases its expression." (PMID 29383199, 2017). "More importantly, miR-370 over-expression inhibited the proliferation, clonogenicity, wound healing and invasion of lung cancer cells in vitro, which were associated with reduced levels of EGFR and HIF-1α expression and the ERK1/2 and AKT activation." (PMID 29152147, 2017). "Notch1 signaling is involved in the upregulation of Survivin expression in lung cancer cells as well, which is synergized by HIF-1α." (PMID 28030818, 2017). "The expression levels of HIF‐1α, GLUT1, and CAIX were associated with poor overall survival of lung cancer patients after induction chemoradiotherapy." (PMID 28028936, 2017). "Associations of HIF‐1α, glucose transporter 1 (GLUT1), and CAIX with chemoresistance of lung cancer were investigated using A549 lung cancer cells under normoxia or hypoxia in vitro." (PMID 28028936, 2017). "PJ supplementation significantly decreased the incidence of lung cancer, secondary to CS, prevented the formation of lung nodules, and reduced mitotic activity and HIF-1α expression in an animal model." (PMID 29333211, 2017). "Mir-622 influences and suppresses metastasis in xenograft model of lung cancer via inhibition of HIF-1α-related EMT signaling." (PMID 29383199, 2017). "A recent study reported that CA suppressed HIF-1α and hypoxia-induced angiogenesis in A549 lung cancer cells and that the mechanisms of the inhibition of hypoxia-induced HIF-1α by CA involve stabilization of HIF-1α by the AKT pathway." (PMID 28165392, 2017). "In this research we find that HIF-1a plays a critical role in the recurrence of lung cancer following hyperthermia treatment as the proliferation and angiogenesis potential of residual NSCLCs and SCLCs are induced by HIF-1a." (PMID 27456341, 2016). "The results showed that knockdown of HIF-1A significantly reduced the expression of OCT4, demonstrating that OCT4 expression can be regulated by HIF1A in lung cancer cells." (PMID 27588392, 2016). "Expression of HIF1A is tightly regulated on transcription and translation level, with increased levels of HIF1A in tumors including lung cancers and under hypoxic conditions." (PMID 27588394, 2016). "Hyperthermia is a promising treatment for human lung cancer, but recurrence of the primary lesion is common, as the residual tumor becomes adapted to heat treatment and growth is induced by hypoxia-triggered HIF-1a expression." (PMID 27456341, 2016). "The upregulation of mir-210 was found to be correlated with the transiently stabilized HIF-1α in lung cancer cell lines after EGCG treatment." (PMID 27941682, 2016). "Survival analysis supports the prognostic value of co-expression of HIF-1α and HectH9 in lung cancer cases." (PMID 27934968, 2016). "In contrast, HIF1α deletion in a KRAS-driven mouse model of lung cancer had negligible effect on tumor burden and progression, whereas a deletion in its isoform, HIF2α increased tumor growth and progression." (PMID 27708247, 2016). "Here, we explored the effects of hyperthermia on HIF-1a expression, proliferation, and lung cancer angiogenesis." (PMID 27456341, 2016). "The direct link between the AC/cAMP/PKA pathway and the activation of HIF-1α has been recently examined in several cell models, such as epithelial-mesenchymal transition in lung cancer, pancreatic beta cell injury, and inflammation in macrophage." (PMID 25722794, 2015). "Among these miRNAs, miR-17 and miR-20a have been reported to directly regulate HIF-1α in lung cancer cells." (PMID 26030758, 2015). "HIF-1α is essential for enabling angiogenesis and metastasis in a variety of solid cancers including lung cancer." (PMID 26528854, 2015).